HRAS (HRas proto-oncogene, GTPase)
Diseases named in the same sentence as HRAS in open-access papers (continued):
Sharing a sentence is not in itself a finding about the gene and the disease.
cancer (continued). "Tipifarnib, in particular, has gained renewed interest as a potential treatment for HRAS-mutant cancers and as part of combination therapy with KRAS G12C inhibitors, such as sotorasib, demonstrating synergistic effects in preclinical lung adenocarcinoma models." (PMID 40597785, 2025). "At the same time, preclinical and early clinical studies have shown that HRAS-mutant cancers may be sensitive to the farnesyltransferase inhibitor tipifarnib." (PMID 39596194, 2024). "Although oncogenic HRAS and KRAS mutations are most frequently found in epithelial cell-derived adenocarcinomas, their impacts have been discussed primarily on the basis of the fibroblast phenotype in the field of aging and cancer biology." (PMID 39456601, 2024). "The HRAS protein is considered a critical target for drug development in cancers." (PMID 38338389, 2024). "Additionally, BAY 11-7082 inhibitor treatment leads to downregulation of several specific oncogenic signaling pathways in NRAS, KRAS, and HRAS mutant cancer cells." (PMID 38982514, 2024). "Similarly, previous studies indicated that targeted demethylation of PDK4 suppresses glycolysis, while m6A sites of HRas proto-oncogene, GTPase targeted by the dm6ACRISPR system can decrease cancer proliferation and metastasis." (PMID 39059495, 2024). "Recently, there has been a renewed hope in the use of FTIs in HRAS-mutant cancers." (PMID 37221195, 2023). "The observation in cancer databases of preferential amplification of KRAS versus HRAS or NRAS might seem counterintuitive if it is already the most abundant isoform." (PMID 36864243, 2023). "This central position to orchestrate hallmarks of life may explain why RAS is so frequently exploited in cancer, where the three RAS genes, KRAS, NRAS and HRAS combined are mutated in 19% of cancer patients." (PMID 36688434, 2023). "Among the 19 patients who developed benign tumours, only one (6%) carried somatic variant in KRAS, 16 (84%) showed a mutated HRAS allele, and two (10%) had mutations in PIK3CA genes; the 13 patients with cancer harboured somatic variants exclusively in the KRAS (31%) and HRAS (69%) genes." (PMID 37636262, 2023). "Therefore, the role of HRAS in cancer is multifaceted and cannot be limited to a single pathway or mechanism." (PMID 37153521, 2023). "The three human Ras genes, HRAS, KRAS, and NRAS, are found frequently mutated in about one-third of human cancers, with KRAS mutations being the most prevalent among the three isoforms (∼86% of cases), and with NRAS and HRAS representing only 11% and 3%, respectively." (PMID 38051103, 2023). "The molecular circadian clock is not disrupted in all cancers, and in particular seems to be maintained (albeit in an altered state) in those driven by mutated HRAS or KRAS." (PMID 37639465, 2023). "However, more recent investigations have shown that HRAS, NRAS and KRAS, when mutated, are each associated with a distinct group of cancer types." (PMID 35204676, 2022). "HRAS is encoded by the RAS protein, which is commonly deregulated in human cancer." (PMID 36358305, 2022). "Similarly, we observed phase-shifted transcript pairs from cancer hallmarks genes like HRAS and CD63 unique to HCT116_PER2KO." (PMID 35552415, 2022). "However, the ability of KRAS to be alternatively prenylated in response to farnesyl transferase inhibitor treatment rendered this approach ineffective for KRAS-mutant cancers, although these inhibitors have shown some efficacy in HRAS-mutant malignancies." (PMID 36334633, 2022).
cancer (continued). "With the realization that HRAS mutations can cause oncogene addiction and activated MAPK signaling in cancer, tipifarnib trials have sought to investigate its effectiveness in pan-cancer patients with and without HRAS mutations." (PMID 35296678, 2022). "Considering the sequence homology between RAS isoforms is 100% identical within the Switch II region, we asked whether the interaction between AGO2 and HRAS or NRAS could be detected endogenously in human cancer cell lines." (PMID 35923912, 2022). "To further validate that RAS84 expression could predict high RAS activity in RAS mutants in individual cancers, we looked at pan-RAS mutation (KRAS, NRAS, HRAS) distributions across RI values per cohort." (PMID 36163168, 2022). "Therefore, this study aims to investigate the nsSNPs of HRAS in understanding its pathogenesis for elucidating the diagnosis and prognosis of cancer using in silico analysis." (PMID 36358305, 2022). "in 2011, reported activated oncogene HRAS or KRAS could increase basal autophagy which was essential to maintain human cancer cell survival in starvation and in oncogenesis." (PMID 36263211, 2022). "A few years ago, wild-type HRas was observed to suppress HRas driven cancer." (PMID 34466166, 2021). "Members of the rat sarcoma (RAS) oncogene family, including Kirsten-RAS (KRAS), Harvey-RAS (HRAS), and neuroblastoma-RAS (NRAS), exhibit the highest mutation frequency in human cancers, with associated mutations being identified in approximately 30% of all cancers." (PMID 34512755, 2021). "In addition, the deregulation of the HRAS gene, which is involved in the proliferation of different cancers, has been reported." (PMID 33765916, 2021). "Interestingly, CASP8 showed similarly increased mutation rate both in early- and late-stage cancers with TMD, while HRAS mutations appeared linked with TMD only in late-stage tumors – pointing toward a timing specificity of TMD-linked evolutionary pressures." (PMID 34307377, 2021). "Although HRAS activity has previously been reported to contribute to most hallmarks of cancer and to drive clinical resistance to cetuximab, it is also likely that HRAS-independent mechanisms contribute, at least in part, to the antitumor activity of tipifarnib in HNSCC models." (PMID 34771475, 2021). "It is worth pointing out that since proteins within Gene EGFR and Gene HRAS affect multiple cancers as compared to proteins within Gene MAPK3 which are unique to each type of cancer, the cost benefit payoff ratio would be higher for Gene EGFR and Gene HRAS than for Gene MAPK3." (PMID 34764329, 2021). "The HRAS, NRAS, and KRAS genes are collectively mutated in a fifth of all human cancers." (PMID 34504076, 2021). "The G12C mutation is a common mutation in the Ras proto-oncogenes (HRAS, KRAS, and NRAS) and, therefore, might be a suitable mutation to target various types of cancer and their causes." (PMID 35062725, 2021).
cancer (continued). "RAS mutations in all cancer types occur mostly in KRAS (85%), followed by NRAS (12%) and HRAS (3%)." (PMID 31941155, 2020). "Over 30% of cancers are driven by mutant Ras proteins, thereinto, one method called catalog of somatic mutations in cancer (COSMIC) confirms that HRas (3%) are the least frequently mutated Ras isoforms in human cancers, where KRas (86%) are the predominantly mutated isoforms followed by NRas (11%)." (PMID 33266473, 2020). "Our data extend this line of work by suggesting that pharmacological inhibition of autophagy, using chloroquine, reduces the release of EV-associated oncogenic DNA (but not EVs themselves) in cancer cells driven by oncogenic HRAS." (PMID 32444772, 2020). "These included many cancer-associated genes such as AKT2, HRAS, TGFBI and UBE2C." (PMID 32437477, 2020). "RAS genes (HRAS, KRAS, and NRAS) are the most frequently mutated gene family in cancer." (PMID 31681587, 2019). "For instance, gain‐of‐function mutations and overexpression of RAS family members (KRAS, HRAS, and NRAS) are among the most prevalent oncogenic lesions in human cancers, and high levels of Ras activity are necessary to maintain the transformed phenotype in some Ras‐driven cancers." (PMID 30422399, 2019). "KRAS has the highest mutation rate compared to HRAS and NRAS in various types of cancers." (PMID 30971271, 2019). "Mutations in the three major Ras isoforms, HRAS, NRAS, and KRAS, which impair GTPase activity and/or the ability of Ras to interact with negative regulators are found in approximately a third of human cancers." (PMID 31497244, 2019). "Although KRAS, HRAS, and NRAS share functional similarities, KRAS missense gain-of-function mutations tend to occur on the 12th codon, while those in HRAS and NRAS occur on the 61st codon and are differentially utilized across cancer types." (PMID 31681559, 2019). "Mutations of KRAS and HRAS in cancer affect the efficacy of chemotherapy; changes in TRP channel expression could overcome drug resistance and increase the sensitivity of cancer cells to chemotherapy." (PMID 31801263, 2019). "Thus, TRPML1 appears generally dispensable for regulating the gain of MAPK signaling, except in the context of HRAS-driven cancer cells that are marked by the profound upregulation of ERK phosphorylation." (PMID 31526156, 2019). "HRAS and KRAS are among the most frequently mutated genes in human cancers." (PMID 30532261, 2018). "From variant analysis of 46 cancer susceptibility genes, we identified 7 pathogenic and likely pathogenic germline variants in 7 genes in 7 (8%) of the 87 patients, namely, MUTYH, RET, TSC2, BRCA1, BRCA2, ERCC2 and HRAS." (PMID 29684080, 2018). "To assess whether our filtering strategy retained known somatic mutations, we tested the impact of this strategy on the hotspot mutations in five known cancer-associated genes: BRAF, RAS family (HRAS, NRAS, and KRAS), and stop-gain NF1 gene mutations." (PMID 30662871, 2018). "Also, while most early studies utilized the activated form of HRAS (generally referred to as RAS), each RAS isoform (HRAS, KRAS and NRAS) has a distinct biological function, and KRAS mutations are much more common in human cancers than NRAS and HRAS mutations." (PMID 28152508, 2017). "SETD2, PTEN, RNF43, HRAS, EPHA2, and BAP1 were also linked to primarily positive associations in more than one cancer type, suggesting that they may play a general role in CGI hypermethylation." (PMID 29125844, 2017). "This provides proof of principle for a new mechanism for knocking out oncogenic HRAS, which may be used therapeutically to treat cancer." (PMID 27195699, 2016).
cancer (continued). "The 3 human RAS genes (HRAS, KRAS, and NRAS) are among the most prevalent drivers of human cancer, with KRAS being mutated in 20-25% of all human tumors and up to 90% in certain cancer types, e.g. pancreatic cancer." (PMID 26028667, 2015). "In many different human cancers, one of the HRAS, NRAS, or KRAS genes in the RAS family of small GTPases acquires an oncogenic mutation that renders the encoded protein constitutively GTP-bound and thereby active, which is well established to promote tumorigenesis." (PMID 25902334, 2015). "Moreover, both PAK1 and HRAS are involved in transduction of proliferation signals and their miss-regulation leads to abnormal signal transduction and cancer." (PMID 25965968, 2015). "Among the cancer cell lines used in this study, both CNE2-S18 and CNE1 cell lines were previously confirmed to have hyper-activated PI3K/AKT signaling due to the PIK3CA and HRAS mutation, respectively." (PMID 25749514, 2015). "This is the first hint that HRAS mutant cancer patients might benefit clinically from MEK inhibitor treatment." (PMID 26544513, 2015). "Since MEK inhibitors block cell growth we wanted to analyze whether induction of apoptosis occurs in HRAS mutant cancer cell lines." (PMID 26544513, 2015). "Clinical characteristics and behavior of HRAS mutant cancer patients have been described scarcely." (PMID 26544513, 2015). "A cleverly conceived transgenic mouse (called RasE Multi-Hit) has been recently developed to study which pathways may cooperate to induce HRAS-driven cancer." (PMID 24489653, 2014). "Thus, we conducted a case–control polymorphic study of HRAS rs12628 to assess the role of this SNP in cancer." (PMID 22618666, 2012). "Although sotorasib was considered KRAS G12C specific and is FDA-approved for KRAS G12C mediated cancers only, studies have indicated it may be suitable for other NRAS or HRAS G12C-mutated cancer, delivering potential to revolutionise the way in which the drug can be used." (PMID 39372214, 2024). "We used “RASless” MEF lines expressing mutant HRAS to investigate whether some of the more common co-mutations observed in human tumors affected their response to growth inhibition by tipifarnib, which is currently in clinical development for HRAS-mutant cancers." (PMID 37503077, 2023). "Furthermore, GEO database (GSE17112) analysis showed that HRAS oncogenic gene set was enriched in GINS1 high-expressed cancer cells, and quantitative real-time PCR, and Western blot results proved that GINS1 enhanced HCC progression through regulating HRAS signaling pathway." (PMID 34414190, 2021). "Knockdown studies showed that the non-mutated WT RAS genes are necessary for growth-factor-mediated signaling to RAS effector pathways in HRAS-, NRAS, and KRAS-mutated cancer cells, indicating that cancer cell response to growth factors may be mediated by WT RAS, not the oncogenic RAS mutant." (PMID 33924994, 2021). "However, HRAS is regarded as an oncogene and is well known for its proliferative role in cancers." (PMID 32062610, 2020). "However, the background of mutant KRAS may be contributing to these findings as mutant HRAS or KRAS cancers are sensitive to enhanced proteotoxic stress and ER stress." (PMID 30860482, 2019). "Although β-catenin- and RAS-destabilizing compounds induced the degradation of HRAS and NRAS, these could be beneficial for the treatment of cancer, because the overexpression of WT-HRAS or -NRAS is known to play roles in the promotion of MT-KRAS-driven tumorigenesis." (PMID 30459318, 2018). "In addition to the recurrent and early 11p LOH event in fusion negative tumors, mutation of FGFR4, KRAS, NRAS and HRAS frequently occurred at an early time point in the cancers evolutionary history." (PMID 25768946, 2015).
cancer (continued). "Interestingly, PIK3CA mutations occurred almost always in combination with HRAS mutations (p < 0.0001), only one case of carcinoma ex pleomorphic adenoma (SDC) carried a PIK3CA mutation without a simultaneous HRAS mutation." (PMID 26053092, 2015). "Mutations in RAS proto-oncogenes (comprising H-, N- and K-RAS) are among the most common in malignant tumours and although RAS isoforms are very similar, KRAS is more frequently found mutated in cancers occurring in 22% of all tumours analysed compared to 8% for NRAS and 3% for HRAS." (PMID 24720724, 2014). "They demonstrated that modified HMLER cells, which were experimentally-derived by transforming normal HMECs with hTERT, SV40 large-T antigen and hRas(V12), could be readily cultured and screened to identify anti-cancer compounds that selectively target cancer stem cells." (PMID 23879992, 2013). "Yet, cancers driven by oncogenic KRAS, HRAS, or NRAS remain strongly SHOC2-dependent, suggesting that these weaker complexes contribute to tumorigenesis." (PMID 41519889, 2026). "FTase proteins (FNTA and FNTB) as well as eight of the 116 PFPs are known cancer-relevant proteins as per COSMIC Cancer Gene Census49 or TCGA50 (KRAS, HRAS, NRAS, RHEB, RHOA, DDX3X, ARID2, and SAV1)." (PMID 39995872, 2025). "Rat sarcoma (RAS) proto-oncogenes play an important role in the development of cancer, with the three RAS genes (HRAS, NRAS and KRAS) being the most commonly activated drivers of cancer within this family." (PMID 40868227, 2025). "KRAS is central in metabolic regulation in pancreatic cancer models, while HRAS and NRAS exhibit distinct functions in other cancer types." (PMID 40906088, 2025). "Studies of cell lines with KRAS G12C mutations generated from ARS-1610 and AMG510 and their effects on cancer cells have shown that downstream effectors are still activated and that the levels of active KRAS and HRAS wild-type proteins are increased." (PMID 40597785, 2025). "This transduction process produced the viral oncogenes HRAS and KRAS, which were later shown, along with NRAS, to play key roles in human cancer." (PMID 40906088, 2025). "Genes like HRAS, CCND1, and CDKN2A are well-known drivers of cancer-related processes, including cell cycle progression, and apoptosis." (PMID 40333905, 2025). "Compared to adjacent normal mammary glands, TSG101-overexpressing carcinomas show higher levels of ERBB3, HRAS, and active AKT (left)." (PMID 40624726, 2025). "CG methylation has been reported to induce conformational changes of iMs from CpG islands of four genes related to cancer (VEGF, C-KIT, BCL2 and HRAS)." (PMID 38180820, 2024). "Mutations in the rat sarcoma viral (RAS) oncogene family, specifically KRAS, HRAS, and NRAS, are among the most prevalent among human tumorigenesis found in 30% of all cancer types included." (PMID 39184150, 2024). "In 1982, the RAS genes HRAS and KRAS were discovered as the first human cancer genes, with KRAS later identified as one of the most frequently mutated oncogenes." (PMID 39732595, 2024). "Concerning gene expression results compared to the BBN induced cancer group, FGFR3 and HRAS (oncogenes) showed strong down-regulated expression levels in both BBN treated with artemisinin group and BBN + cisplatin group pre-treated by artemisinin." (PMID 39118085, 2024). "We find that oncogenic NRAS, KRAS, and HRAS activate the expression of IkappaBalpha (IκBα) and BAY 11-7082, an inhibitor of IκBα kinase, attenuates the growth of NRAS, KRAS, and HRAS mutant cancer cells in cell culture and in vivo mouse model." (PMID 38982514, 2024). "An OCSCC cohort more than twice the size of the TCGA cohort allowed us to find additional cancer driver genes that are frequently affected in CNA-quiet OCSCC, notably PIK3CA, RAC1, and TERT, besides the previously established HRAS and CASP8." (PMID 39428388, 2024).